ZEB1 (zinc finger E-box binding homeobox 1)
Diseases named in the same sentence as ZEB1 in open-access papers (continued):
Sharing a sentence is not in itself a finding about the gene and the disease.
tumor (continued). "The expression of E‐cadherin is essential for the tumor‐initiating capacity, while mesenchymal features with high ZEB1, ZEB2, and SNAIL can impair this capacity." (PMID 39092293, 2024). "Upregulation of ZEB1 had been found in various tumors and a positively correlation between ZEB1 expression and tumor malignant progression was verified." (PMID 38954708, 2024). "A recent study reported that TAMs depend on ZEB1 to maintain a tumour-promoting phenotype and protumour functions, highlighting the importance of ZEB1 in TAMs." (PMID 38183060, 2024). "Similar to unchallenged Zeb1-dcKO mice, tumor-bearing Zeb1-dcKO mice also had decreased frequencies and numbers of splenic cDC1, as compared with tumor-bearing WT mice." (PMID 37863917, 2023). "As a member of the zinc finger protein family, ZEB1 induces epithelial-mesenchymal (EMT) transformation of tumor cells." (PMID 37435030, 2023). "It reduces the tumor sphere formation and directly declines ZEB1 expression and also suppress the stem cell phenotype." (PMID 36740668, 2023). "The increased FTO strengthens the stability of ZEB1 mRNA transcripts, which results in chemoresistance and epithelial-mesenchymal transition of tumor cells, indicating neutrophils control tumor progression by impacting the RNAs regulators in tumor cells." (PMID 37928272, 2023). "High expression of LINC01296 in CRC and NSCLC cells upregulates ZEB1/ZEB2 by acting as miR-141-3p sponge to promote tumor EMT, invasion, and migration." (PMID 37511619, 2023). "Zeb1 expression is accompanied by the downregulation of vimentin, which constrains tumor invasion and migration." (PMID 38132928, 2023). "Particularly, we found ZEB1 was highly expressed in CRC tumor tissues compared with adjacent normal tissues in two independent datasets from GEO database." (PMID 37749132, 2023). "Although ZEB1 is best known for triggering an EMT, we found that ZEB1-high in BRAF/Braf-mutant CRCs paradoxically correlated with low tumor budding and a reduced EMT signature, the opposite than in KRAS-mutant CRCs." (PMID 37870961, 2023). "Many studies have proposed that EMT is crucial for VM formation and tumor progression, with ZEB1 as an essential EMT inducer that is elevated in colorectal cancer specimens showing EMT features both in vivo and in vitro." (PMID 37810976, 2023). "Next, we investigated the expression of the ZEB1 protein by immunohistochemistry (IHC) in all 14 tumor lesions of our cohort." (PMID 37076857, 2023). "This study concluded that TRIM9 was a tumor suppressor that interacted with ZEB1 and accelerated ZEB1 protein degradation via the ubiquitin-proteasome pathway (UPP)." (PMID 37124931, 2023). "This process is regulated by transcription factors in tumor cells (Snail 1, Slug, ZEB1, Twist, FOXC2, etc.)and signaling pathways from the tumor microenvironment (WNT, Notch, Hedgehog, TGFβ, FGF, EGF, HGF signaling, etc.)." (PMID 38139030, 2023). "Notable examples include ZEB1, a major inducer of EMT, as well as LAMC1, an extracellular matrix protein associated with tumor invasion and metastasis." (PMID 37117180, 2023). "For individual tumor cells, however, we do observe the expected positive correlation between PD-L1 and ZEB1 expression in each scenario." (PMID 37638024, 2023). "Our previous study also showed that TRIM26 suppresses HCC by ubiquitinating ZEB1, a crucial driver of tumor by inducing the EMT in tumor epithelial cells." (PMID 36707504, 2023). "In melanocytes, a shift from ZEB2 to ZEB1 was previously shown to modulate the balance between cell differentiation and proliferation and to thereby drive tumor initiation and secondary site colonization." (PMID 36765930, 2023).
tumor (continued). "Zinc finger E-box binding homeobox 1 (ZEB1), a transcriptional repressor, has recently been demonstrated to increase tumor cell invasion and metastasis." (PMID 37834263, 2023). "Thereby, the M13HS-2 and -8 ZEB1-KO tumor hybrids showed markedly increased SNAIL expression levels, whereas rather weak SNAIL expression levels were observed in HS578T-Hyg ZEB1-KO cells." (PMID 38139138, 2023). "Given that Zeb1 expression in DC was required for activation of tumor infiltrating CD8+ T cells, we next investigated the role of Zeb1 in cross-presentation of cell-associated antigens." (PMID 37863917, 2023). "ZEB1 mediates RAS/AKT-induced resistance to anoikis (anchorage-independent survival) that allows migratory cancer stem cells to shed from the primary tumor, invade the surrounding stroma, and eventually metastasize." (PMID 37870961, 2023). "qRT-PCR ascertained LINC00667, miR-143-3p, and ZEB1 mRNA profiles in the cancerous and non-tumor tissues of ccRCC patients." (PMID 37827696, 2023). "The tumor sections were stained with HE staining and observed under a microscope, and the expression of zeb1 protein in tumor cells was detected by immunohistochemistry." (PMID 38070058, 2023). "The expression of the EMT markers Rhoa and Zeb1 in primary tumours was significantly higher in mice in the GAA diet group than in mice in the control group." (PMID 37370109, 2023). "In contrast, the CD4+ and CD8+ T cells in tumor dLN remained poorly activated, and their numbers were comparable between WT and Zeb1-dcKO tumor-bearing mice." (PMID 37863917, 2023). "Thereby, the highest decrease was observed in the M13HS-2 ZEB1-KO tumor hybrids (about two-thirds less compared to M13HS-2 cells), whereas only a moderate reduction was found in the M13HS-8 ZEB1-KO cells (about one-third less than of M13HS-8 cells." (PMID 38139138, 2023). "To exclude the influence of deficits in splenic cDC1 numbers on the antitumor T cell response in Zeb1-dcKO mice, we performed splenectomy before tumor inoculation." (PMID 37863917, 2023). "Particularly, the CMS4 categorization was linked to an EMT signature that included a notable decrease in the microRNAs that control tumor suppression via ZEB1 and ZEB2." (PMID 37834263, 2023). "In in vitro cancer cell lines and an in vivo spontaneous HCC mouse model, DIO3OS markedly represses tumor development via its suppressive role in CSCs through downregulation of zinc finger E‐box binding homeobox 1 (ZEB1)." (PMID 37271897, 2023). "The number of invading cells, indicated by Zeb1+ cells infiltrating outside the gross tumor mass, was significantly reduced by STAT3 or SRF knockdown." (PMID 37558923, 2023). "Many studies have discovered that ZEB1 is involved in the regulation of EMT, which is closely associated with metastasis of tumor cells." (PMID 36805336, 2023). "Many of the DEGs were involved in ferroptosis (Ptgs2), enhanced T-cell function (Lef1), regulators of EMT (Zeb1, Zeb2, Vimentin, and Sfrp2), and fibrosis (Col1α1 and Acta2) in the tumor microenvironment." (PMID 36835036, 2023). "The miR/ZEB1 axis can be regulated by long non-coding RNAs (lncRNAs) or circular RNAs (circRNAs), which regulate tumor malignancy in several cancers, including lung, gastric, and ovarian." (PMID 37444447, 2023). "In contrast, the migratory activity of the M13HS-2 ZEB1-KO and -8 ZEB1-KO variants was virtually completely abrogated in comparison to the M13HS-2 and -8 tumor hybrids." (PMID 38139138, 2023). "Experimental findings have demonstrated that CAFs lose their ability to enhance metastatic activity of tumor cells when depleted of ZEB1." (PMID 38124183, 2023). "For instance, the E-cadherin transcriptional repressors zinc finger e-box binding homeobox 1 (ZEB1) and 2 (ZEB2) have been implicated in EMT and tumor metastasis." (PMID 36827545, 2023).
tumor (continued). "In line with other experiments in this study, the downregulation of ZEB1 in LS174T cells inhibited their tumorigenic capacity (tumor volume), whereas ZEB1 downregulation in RKO cells promoted it." (PMID 37870961, 2023). "They induced the expression of Snail, Twist or Zeb1 in vivo and demonstrated that Zeb1 successfully stimulated latent disseminated tumor cells to enter a tumor-initiating state and then generated macro-metastasis." (PMID 36768876, 2023). "TRIM58-ZEB1 interaction accelerated degradation of ZEB1 protein, thus further leading to the augment of tumor behaviors." (PMID 36644609, 2023). "Of note, Zeb1 was shown to have tumor-suppressive function in T cells: Zeb1 knockout mice develop mature (classical) T-ALL." (PMID 36950387, 2023). "In contrast, the mammosphere formation capacity of the M13HS-2 ZEB1-KO and -8 ZEB1-KO tumor hybrids was markedly and significantly reduced." (PMID 38139138, 2023). "The ABCA8 is a tumor suppressor gene whose downregulation transforms epithelium into mesenchyme, via the ERK/ZEB1 signaling pathway, promoting tumor progression." (PMID 36703136, 2023). "A positive feedback loop between stiffness-induced zinc finger E-box binding homeobox 1 (ZEB1) expression and ZEB1/LOXL2-induced ECM stiffness remains tumor cells in a mesenchymal state." (PMID 36906534, 2023). "Because of ZEB1’s role in tumor initiation and progression, the overexpression of ZEB1 for therapeutic purposes naturally raises concerns." (PMID 38097578, 2023). "The balance between AGR2 and ZEB1 is suggested to govern the aggressiveness and invasive phenotype of tumor cells." (PMID 36329620, 2023). "NF-κB and AP-1 regulate the expression of multiple genes involved in tumor proliferation and metastasis, including those encoding cyclin D1, cyclin E, Myc, MMP-9, MT1-MMP, uPA, Snail, and ZEB1." (PMID 37894738, 2023). "ZEB1 is highly expressed in tumor tissues of multiple cancers including neuroblastoma, lung cancer, breast cancer, and pancreatic cancer, and its expression is positively correlated with the invasiveness of cancer cells." (PMID 36805336, 2023). "Skp2 orchestrates with Myc to recruit p300 to the promoter of zinc finger E-box binding homeobox 1 (Zeb1), which leads to induction of Zeb1 transcription, finally promoting tumor migration and invasion." (PMID 37089937, 2023). "M13HS-2 and -8 tumor hybrids co-expressed ZEB1 and SNAIL, whereby the SNAIL expression levels were higher in the M13HS-2 than in M13HS-8 cells." (PMID 38139138, 2023). "Immunohistochemistry confirmed that ZEB1 was co-expressed with the epithelial marker cornifin B in individual tumor cells." (PMID 37076857, 2023). "And both in vitro and in vivo models have confirmed that overexpression of ZEB1 promoted invasive capability of multiple kinds of tumor cells." (PMID 36644609, 2023). "Thereby, particular attention was drawn to a prospective mixed/hybrid E/M phenotype and CSC properties due to SNAIL and ZEB1 co-expression of M13HS tumor hybrids and EMT-related properties." (PMID 38139138, 2023). "The enhancement of tumor cell plasticity is an important driving force for the progress of malignant tumors, and ZEB1 is the key factor mediating cell plasticity." (PMID 36644609, 2023). "Rescue assays were conducted for to verify the functions of the LINC00667-miR-143-3p-ZEB1 axis in tumor cells (P<0.05)." (PMID 37827696, 2023). "The knockdown of these lncRNAs (oncogenic) downregulated the expression of ZEB1, Twist, Notch, and Slug/Snai1 and vice versa in overexpression studies for the tumour-suppressive lncRNAs." (PMID 37372103, 2023).
tumor (continued). "Zeb1 is required for expression of PD‐L1 on invading lung cancer cells, but there are tumours that show high EMT but low PD‐L1 expression profile." (PMID 36625080, 2023). "Consistent with the increased tumor growth, Zeb1-dcKO mice showed a marked decrease in the recruitment and activation of effector CD8+ T cells and a mild reduction in numbers of effector CD4+ T cells in B16F10 tumors despite normal cDC1 infiltration." (PMID 37863917, 2023). "Subsequently, those mice also developed lung metastases, indicating that Zeb1 expression in vivo can activate EMT to facilitate the acquisition of tumor initiation and metastasis." (PMID 36768876, 2023). "The numbers of splenic CD4+ and CD8+ T cells were slightly but significantly declined in tumor-bearing Zeb1-dcKO mice, consistent with the decreased numbers of splenic cDC1." (PMID 37863917, 2023). "PTEN, for example, is one of the most well-known tumor suppressors, and ZEB1 and ZEB2, the most important genes involved in EMT, are at the top of the table." (PMID 37854681, 2023). "LS174T and RKO cells with basal and downregulated levels of ZEB1 were xenotransplanted in immunodeficient nude mice and tumor formation was evaluated over time." (PMID 37870961, 2023). "ZEB1/ZEB2 is a critical regulator in various tumor types and is downstream of nuclear factor kappa B (NF-κB)." (PMID 37296849, 2023). "It has been reported that ubiquitination modification on ZEB1 involved in maintenance of ZEB1 stability plays important roles in tumor progression." (PMID 36906615, 2023). "This regulatory function of ZEB1 promotes the emergence of invasive and/or stem-like states within the tumor." (PMID 37511550, 2023). "Surprisingly, we observed a high activity of the EMT-activator ZEB1 in metastatic OSCC cells with epithelial differentiation, which was confirmed by co-expression of ZEB1 and cornifin-B protein in individual tumor cells." (PMID 37076857, 2023). "We observed nuclear ZEB1 expression in similar tumor areas as cytoplasmic cornifin-B expression, which served as a marker of epithelial differentiation." (PMID 37076857, 2023). "Through binding with ZEB1 protein, TRIM58 enhanced ZEB1 protein degradation via ubiquitin-proteasome pathway so that TRIM58 was capable of minimizing ZEB1-mediated promotion of tumor migrated and survival capability." (PMID 36644609, 2023). "Subsequent functional experiments provided novel evidence that TRIM9 exhibited tumor suppressive effects through the interaction with ZEB1." (PMID 37124931, 2023). "LINC01711 knockdown results in downregulating ZEB1, a crucial transcription factor that promotes tumour cell invasion and EMT." (PMID 37891744, 2023). "Taken together, these results suggest that ZEB1 has a tumor-promoting effect in Kras-mutant models of intestinal tumorigenesis but, contrary to expectations, a tumor suppressive effect in Braf-mutant counterparts." (PMID 37870961, 2023). "And, further detailed experiments depicted novel mechanism that TRIM58 exhibited tumor inhibitory effects via interaction with ZEB1." (PMID 36644609, 2023). "In our samples, ZEB1 mRNA expression was lower in tumor than in healthy MGTs, as previously reported by other authors in HBC." (PMID 36899736, 2023). "The amount of Zeb1-positive cells, which indicate invading cells, was also reduced outside the gross tumor mass by DFS." (PMID 35978012, 2022). "Zinc finger E-box binding homeobox 1 (ZEB1), was also related to tumor metastasis by promoting cell migration and invasion." (PMID 35483343, 2022). "The regulation of ZEB1 through a feedback loop can mediate tumor progression and metastasis by communication among key signaling pathways." (PMID 35454770, 2022).
tumor (continued). "For instance, miR-200 is found to suppress tumor progression via binding to ZEB1 (Zinc finger E-box-binding homeobox 1) and E-cadherin, eventually inhibiting the EMT process." (PMID 35008971, 2022). "Together, our results suggest that EMT is associated with reduced but intermediate response to Erlotinib whereas repression of ZEB1 signature and upregulation of MYC signature is associated with tumor-type agnostic resistance at the Pan-cancer scale." (PMID 35618721, 2022). "Hypoxia in the tumor microenvironment can promote the expression of transcription factor ZEB1, thereby upregulating CCL8 production by directly binding to the CCL8 promoter region." (PMID 35281057, 2022). "High levels of ZEB1 expression in the tumor ECs (TECs) of lung cancer have been shown to exacerbate the tumor microenvironment, including increased metastatic potential and decreased anti-tumor immunity driven by EC-secreted TGF-β." (PMID 35130955, 2022). "In particular, our results demonstrated that Zeb1, as a transcription factor, directly increases the expression of multiple glycolytic genes, thus promoting the Warburg effect and tumor aggressiveness in vitro and in vivo." (PMID 35246504, 2022). "Clinically, YTHDF2 expression exhibited a positive correlation with ZEB1 expression in both TCGA database and BC tumor tissues (n = 82) from our independent cohort." (PMID 36302751, 2022). "In previous papers, some tumor-promoting genes (like Snail1, Slug, ZEB1/2, MMP2, MMP9, and ADAM12) were found to be modulated by TGF-β." (PMID 35794983, 2022). "ZEB1 is an essential factor in the regulation of the initiation and development of tumours through EMT." (PMID 36499447, 2022). "Conversely, ablation of Zeb1 in KP*C tumours results in a dramatic histological and functional phenotype wherein tumours are rendered almost entirely epithelial, with significantly reduced metastatic burden." (PMID 36088504, 2022). "For example, EMT transcriptional factors, including Snail, Zeb1, and Twist1, can attract cancer-related immune cells and shape tumor microenvironment into a protumor subtype." (PMID 35990996, 2022). "Members of the miR-200 family act as tumour-suppressive miRNAs, enhancing the expression of E-cadherin and suppressing the expression of ZEB1 and ZEB2." (PMID 36499447, 2022). "Upon HIF1α knockdown, the number of tumor cells crossing the membrane was significantly decreased, and this inhibition partially retrieved after ZEB1 overexpression." (PMID 35589690, 2022). "Previously, we reported that epithelioid UM cells exhibit a high ZEB1 expression, whereas spindle-type tumor cells show the opposite." (PMID 35404029, 2022). "Zinc finger E-box binding homeobox 1 (ZEB1) is a transcription factor that promotes tumor invasion and metastasis by inducing epithelial-mesenchymal-transition (EMT) in carcinomas." (PMID 35404029, 2022). "The results revealed significant correlations between HNRNPC expression levels and tumor infiltration (P = 0.019) and recurrence (P < 0.001), while ZEB1 expression was significantly correlated with recurrence (P < 0.001)." (PMID 35963855, 2022). "Accordingly, the abundance of cellular miR-200 in liver metastasis tissue is much higher than in the primary tumor tissue, and this miRNA is known to target ZEB1 and enhance subtype transition from M to E in the metastasized cells." (PMID 35849310, 2022). "RT-PCR analysis of EMT-associated factors showed that the orthotopic tumor had an increased expression of EMT-associated factors Vimentin, Twist, ZEB1, SNAIL and ZEB2 as compared to metastatic tissues." (PMID 35837106, 2022).